INS (insulin)
Diseases named in the same sentence as INS in open-access papers (continued):
Sharing a sentence is not in itself a finding about the gene and the disease.
diabetes (continued). "The decrease in blood glucose concentration observed in this retrospective study was statistically significant and it was noted that 47% of patients with diabetes were able to successfully discontinue their diabetic treatment including insulin therapy." (PMID 38362147, 2024). "Diabetes occurs when blood sugar (glucose) levels are too high due to insufficient insulin production by the pancreas or improper body response to insulin." (PMID 39040717, 2024). "None of the patients had clinical or biochemical signs of overt diabetes; and their per-operative insulin levels were within normal levels for healthy age-matched controls (5–19 mIE/L)." (PMID 39039509, 2024). "The Omnipod 5 pump device consists of a Bluetooth-enabled pod with insulin, a Dexcom G6 sensor that communicates directly with the pod, and a personal diabetes manager device that sends glucose values commands to the pod." (PMID 39091290, 2024). "Diabetes, a metabolic disorder, is marked by high blood sugar levels resulting from insufficient insulin secretion or activity." (PMID 39538244, 2024). "On the other hand, when insulin levels remain stable in diabetes patients, an increase in glucagon leads to hyperglycaemia and glycosuria." (PMID 38579770, 2024). "Diabetes is a widespread metabolic disorder and results from insulin resistance and impaired insulin secretion." (PMID 39114126, 2024). "In diabetes management, MN systems for insulin delivery improve glycemic control and patient compliance." (PMID 39458672, 2024). "Only oral hypoglycemic medications and insulin have been used to treat diabetes mellitus, with the former being known to have substantial side effects." (PMID 38380214, 2024). "Self-monitoring of blood glucose (SMBG) is a cornerstone of diabetes management, especially for patients on insulin therapy." (PMID 39188431, 2024). "The role of the diabetes team is essential during follow-up to periodically review the correct diabetes management and the use of the insulin pump, to maintain over time the optimal glycaemic control reached." (PMID 39457190, 2024). "Stem cell therapy is an effective treatment for diabetes and other pancreatic‐related diseases, which can be achieved by inducing their differentiation into insulin‐secreting cells." (PMID 38599852, 2024). "Both simple calculators and rule-based approaches are used throughout diabetes care in various contexts, such as for insulin dosing or clinical alerts." (PMID 37979006, 2024). "The progressive nature of type 2 diabetes mellitus leads to the need for insulin therapy in a significant proportion of patients." (PMID 38433545, 2024). "Since, oxidative stress has been demonstrated to participate in the progression of diabetes which plays an important role during diabetes, including impairment of insulin action and elevation of the complication incidence." (PMID 38716223, 2024). "Very low-cost hardware to create an insulin pump has potential to provide more affordable and equitable diabetes care." (PMID 39090697, 2024). "Type 2 diabetes mellitus (T2DM) is a progressive disease characterized by reduced insulin secretion, increased insulin resistance, and disorders of glucagon metabolism." (PMID 39526249, 2024). "It has a potent role in diabetes as it has the potential to promote glucose uptake and enhance insulin sensitivity." (PMID 38543143, 2024). "Diabetes mellitus (DM) refers to a group of metabolic disorders characterized by high glucose levels in the blood and insufficient production or effectiveness of insulin by the pancreas." (PMID 38982468, 2024). "Users can initiate insulin bolus deliveries through the diabetes manager or the pump’s quick bolus buttons, providing flexibility in administration methods." (PMID 39065641, 2024).
diabetes (continued). "The hypoglycemic effect and insulin bioavailability were tested in a type 2 diabetes mouse model, showcasing the potential to improve diabetes management through oral delivery, thus reducing the reliance on injections and enhancing patient compliance." (PMID 38675454, 2024). "The condition of diabetes mellitus (DM) is described as a part or total deficiency in insulin action, specifically pathway-specific resistance to insulin and progression of specific illness in the glomerulus, the retina peripheral nerve, which defines all forms of diabetes." (PMID 39674630, 2024). "Previous research has shown that interleukin-22 (IL-22) can suppress β-cell stress, reduce local islet inflammation, restore appropriate insulin production, reverse hyperglycemia, and ameliorate insulin resistance in preclinical models of diabetes." (PMID 38811532, 2024). "GLUT4 is the primary insulin-sensitive isoform that becomes downregulated during diabetes, while GLUT1 is the primary basal isoform." (PMID 38400070, 2024). "Diabetes is a progressive disease, and as endogenous insulin secretion declines, a significant proportion of patients will require insulin to manage their blood glucose." (PMID 38778253, 2024). "MODY belongs to one subtype of special diabetes characterized by autosomal-dominant inheritance and early-onset insulin secretion defect." (PMID 39221224, 2024). "Pancreatic β-cells are responsible for insulin secretion, and protecting these cells helps prevent diabetes." (PMID 39188917, 2024). "Heightened succinate levels in people with diabetes and animal models of this disease hint at a relationship between succinate and insulin resistance, disturbed glucose metabolism and co-existing conditions." (PMID 38182909, 2024). "Given that STC1 colocalizes with insulin in beta-cells, its suitability as a diabetes marker has been considered." (PMID 38712328, 2024). "Insulin-producing pancreatic β cells play a crucial role in the regulation of glucose homeostasis, and their failure is a key event for diabetes development." (PMID 38607078, 2024). "These brief measures adequately highlight the reduction in burden, including increase in insulin delivery device satisfaction, decrease in diabetes impact on quality of life, and increase in sleep quality." (PMID 37782904, 2024). "As we have shown in prior work, β-cell dedifferentiation is preceded by impaired insulin secretion, consistent with the evolving pathophysiology of diabetes, characterized by an early and reversible impairment of insulin secretion." (PMID 38335173, 2024). "The results also showed that glucose/insulin metabolism contributed to the MSNA response to exercise even before the development of overt diabetes." (PMID 38050866, 2024). "An experimental study suggested that both restoration of glycemic control and retinal insulin signaling can normalize diabetes-induced retinal abnormality via mediating Akt kinase activity, the expression of inflammatory mediators, and lipid synthetic pathway." (PMID 38952394, 2024). "Approximately two months after initiating therapy, the patient manifested destructive thyroiditis and fulminant type 1 diabetes mellitus, thus necessitating intensive insulin therapy." (PMID 38559614, 2024). "Because MASLD is so common, it should be suspected in anyone with abdominal obesity or impaired insulin sensitivity (diabetes or pre-diabetes)." (PMID 39339660, 2024). "Previous reports have demonstrated that the QUICKI index is one of the simplest and best evaluated and validated surrogate indices with higher predictive power and accuracy for determining insulin sensitivity/resistance and the development of diabetes." (PMID 38715798, 2024). "Polyamines play a central role also in diabetes mellitus, as they prevent the upregulation of glucose and ketone and, similarly to insulin, counteract the disease." (PMID 38918813, 2024).
diabetes (continued). "Prescriptions of insulin, diabetes supplies and diabetes medical devices including continuous glucose monitoring systems and insulin pumps have all been provided free of charge." (PMID 38922417, 2024). "In adults with type 1 diabetes, use of a fully closed-loop insulin delivery system had significant quality-of-life benefits and provided a welcome break from the day-to-day demands of living with diabetes." (PMID 38426909, 2024). "In the diabetes group, 65 (16%) women received medication for diabetes, with most of them (57, 88%) receiving metformin, and a small number insulin (2, 3%) or both (6, 9%)." (PMID 39627143, 2024). "Insufficient diabetes education, poor adherence to insulin therapy, and delayed T1DM diagnosis are pivotal in precipitating DKA episodes." (PMID 38590482, 2024). "Diabetes mellitus is defined as raised blood glucose levels due to several factors such as a defect in insulin secretion, increased insulin resistance at the receptors, or a combination of both." (PMID 39583394, 2024). "In the management of diabetes, nanoparticles have different purposes, mainly to provide insulin release in response to changes in glucose concentration, thus reducing the risk of hypoglycemia." (PMID 39000136, 2024). "Diabetes Mellitus (DM) is a condition in which blood glucose levels remain high in the face of insufficient insulin production and/or reduced insulin sensitivity." (PMID 38805474, 2024). "Authors in this study discovered that oral consumption of PA led to inappropriate activation of the insulin counterregulatory hormonal network that is especially needs attention in the context of diabetes studies." (PMID 39478962, 2024). "The rest of the participants (32%) used 2 basal insulin injections and 1 mealtime insulin injection for diabetes control." (PMID 38678194, 2024). "The scores obtained for the oral glucose insulin sensitivity-derived mixed meal test were higher in subjects who scored higher on the Diabetes Dietary Quality index (β 0.89, 0.39, p < 0.05)." (PMID 39458507, 2024). "In the medical category, significant associations were found between LLA and diabetes treatment, where the group who had LLA used “diet only” to a higher extent (45.1% vs. 39.8%), received insulin more (11.3% vs. 4.3%) and tablets less (36.8% vs. 51.1%)." (PMID 39217619, 2024). "The two most common forms of diabetes are type 1 diabetes, which is characterized by a decrease in insulin production, and type 2 diabetes, which is characterized by an impaired insulin response." (PMID 38175421, 2024). "Individuals on insulin treatment demonstrated poorer knowledge and awareness of diabetes and diabetes eye screening." (PMID 39587498, 2024). "When tested on a mouse model of diabetes, Con-Ins G1 also lowered blood glucose with a 10-fold higher potency compared to human insulin." (PMID 38251250, 2024). "A higher risk of death was also observed in the third tertile of T2D duration (HR, 1.75; 95% CI, 1.12-2.71) and in those taking diabetes medication (insulin HR, 2.01; 95% CI, 1.25-3.23; and oral medications HR, 1.40; 95 CI, 1.03-1.91)." (PMID 39106069, 2024). "Glucose-responsive hydrogels find more extensive application in diabetic disease management compared to cancer therapy, primarily due to the higher prevalence of diabetes and the urgent need for precise insulin delivery in diabetic patients." (PMID 39057463, 2024). "Despite the effectiveness of insulin injections in managing hyperglycemia in type 1 diabetes mellitus (T1DM), they fall short in addressing autoimmunity and regenerating damaged islets." (PMID 39120188, 2024). "Diabetes mellitus (DM) is an umbrella term referring to a range of metabolic disorders that manifest as an inability to control blood sugar as a result of defects in insulin secretion, action, or both." (PMID 39337292, 2024). "CGM data can assist providers in tailoring insulin and diabetes medications and lifestyle changes for people with ESKD." (PMID 39112642, 2024).
diabetes (continued). "Diabetes mellitus, commonly known as diabetes, is a chronic disease that develops when the pancreas cannot produce enough insulin or when the body cannot effectively use the insulin it produces." (PMID 39000969, 2024). "Practical guidance on open source and commercial automated insulin delivery systems: a guide for Healthcare professionals supporting people with insulin-requiring diabetes." (PMID 39196351, 2024). "A WBC count can also predict diabetes independently of two previously identified predictors of diabetes: insulin resistance and insulin secretion." (PMID 38667173, 2024). "The anti-hyperlipidemic effect of ARB in diabetes was attributed to the improved release and sensitivity of insulin, which promotes the uptake of lipids and enhances lipogenesis." (PMID 39458984, 2024). "Long-term insulin treatment rescued the majority of GLUT protein expression alterations in the lung during diabetes, as well as GLUT-4 and -8 trafficking to the pulmonary cell surface." (PMID 38786744, 2024). "While insulin continues to be the mainstay of therapy in type 1 diabetes mellitus, its use in type 2 diabetes mellitus is limited to the presence of comorbidities such as chronic kidney disease, infection, and surgery." (PMID 38654804, 2024). "DrD is characterized by advanced age, high hemoglobin A1c, prolonged diabetes duration, frequent insulin use, and minimal apolipoprotein E4 presence." (PMID 39571101, 2024). "Overproduction of ROS and a diminished antioxidant status resist insulin sensitivity, beta-cell malfunction, and increased glucose intolerance, which ultimately trigger diabetes." (PMID 38090734, 2024). "Furthermore, regular exercise in older adults with diabetes is widely used to prevent muscle breakdown and decline in physical function associated with the aging process, contributing to improved glycemic control, insulin resistance, body fat, lipid profiles, and cardiovascular health." (PMID 38612998, 2024). "Consistent with an impact on insulin secretion, carriers displayed a younger age at diagnosis of diabetes and a lower BMI." (PMID 38743124, 2024). "BMT has the potential to revolutionize the treatment of diabetes by producing functional insulin-secreting β-cells." (PMID 39014283, 2024). "As for late toxicities, one patient with diabetes mellitus needing insulin injections and taking antiplatelet and anticoagulant drugs developed grade 3 hematuria and bladder tamponade." (PMID 38778824, 2024). "Although the broader demographic characteristics (gender, ethnicity, mode of insulin delivery, type of diabetes) were similar across both age groups, there were some key differences." (PMID 39170849, 2024). "A retrospective cross-sectional study was conducted by including all adults from the National Health and Nutrition Examination Survey cycles 2013-2016 and excluding any pregnant women, heart disease, diabetes, and those currently taking insulin." (PMID 38660513, 2024). "These compounds have the potential to enhance glucose metabolism and improve insulin sensitivity, making S. polyanthum an intriguing natural product worth exploring for diabetes management." (PMID 39050386, 2024). "There are several methods of treating diabetes including insulin, allopathic homeopathic, and traditional herbal medicines." (PMID 38658923, 2024). "One of the most successful examples of this mode of production is that of human insulin, which is an essential biopharmaceutical for the treatment of diabetes." (PMID 39387713, 2024). "This is particularly important, as enhanced insulin sensitivity helps regulate blood sugar levels and can prevent the onset of diabetes." (PMID 39734671, 2024). "Studies have shown that insulin resistance (IR) is prevalent in type 2 diabetes mellitus and obese populations, and the classic method for assessing insulin sensitivity is the hyperinsulinemic-euglycemic clamp test." (PMID 38745171, 2024).
diabetes (continued). "The effectiveness of TM also appears to be influenced by the concurrent use of advanced diabetes technologies, such as continuous glucose monitors and automated insulin delivery systems." (PMID 39758346, 2024). "In an experimental setting, it is also inversely correlated with the response to prandial insulin in a group of individuals with diabetes." (PMID 38654804, 2024). "Four of the 14 donors were under medication: one donor had dyslipidaemia and took pravastatin, another had hypertension regulated by losartan, and two donors had diabetes controlled by insulin." (PMID 39479185, 2024). "The most notable example is implementation of insulin cost-sharing cap laws, which place limits on out-of-pocket expenses for insulin, and in some cases, diabetes technology." (PMID 39087202, 2024). "The hexamer-to-monomer transition is a slow process, and this predicament has spurred the engineering of a fast-acting monomer insulin analog for diabetes." (PMID 38425548, 2024). "Aspalathin, a distinctive flavonoid in rooibos, has shown promise in regulating blood sugar levels by improving insulin sensitivity and reducing fasting glucose levels, making it a beneficial dietary supplement for diabetes management." (PMID 39199168, 2024). "The differentiation of beta cell surrogates from embryonic stem cells has potential as a diabetes therapy and can be used to model “environmentally naive” insulin secretion." (PMID 38959864, 2024). "Our study demonstrates a small but non-significant difference between HbA1c and GMI, which can help in the future to more precisely individualize the insulin management of patients with diabetes mellitus." (PMID 38650779, 2024). "Short-term dietary reduction of branched-chain amino acids has been shown to acutely decrease meal-induced insulin secretion and enhance postprandial insulin sensitivity in individuals with diabetes." (PMID 39081700, 2024). "For example, adults with T2DM who manage their condition with insulin instead of tablets experience diabetes distress related to hypoglycemia and powerlessness." (PMID 39574786, 2024). "The 2010s witnessed the approval of insulin degludec (Tresiba) in 2014, an ultra-long-acting insulin with a duration of action of up to 42 hours, offering even more flexibility in diabetes management." (PMID 39734941, 2024). "Studies show that zinc can enhance pancreatic β-cell function, improving insulin levels and metabolic status in patients with diabetes." (PMID 39839287, 2024). "MISROS exhibited significant positive correlations with obesity (waist circumference), insulin resistance (HOMA-IR), diabetes (HbA1c), fasting blood glucose, and insulin in both sexes." (PMID 39453155, 2024). "In an insulin-producing beta-cell line, DLK was shown to become activated by prodiabetogenic signals, inhibit insulin synthesis and secretion, and induce apoptosis, thus promoting the pathogenesis of diabetes mellitus type 2." (PMID 38391946, 2024). "Diabetes is a multifactorial disease, but insufficient insulin secretion due to inadequate functional beta cell mass and dysregulated, often increased, glucagon secretion are fundamental to essentially all forms of diabetes and contribute to hyperglycemia." (PMID 39433176, 2024). "Understanding the interplay among ucOC, glucose, and insulin secretion holds significant clinical implications for metabolic disorders such as type 2 diabetes mellitus." (PMID 39125265, 2024). "In the HG state, the activation of several inflammatory cells and the release of inflammatory mediators contribute to vascular endothelial cell necrosis and reduced insulin sensitivity, key factors in the development of various diabetes-related complications." (PMID 38193803, 2024). "After six weeks of diabetes induction by alloxan, a significant (P<0.05) increase in glucose and HbA1c and a reduction in insulin were noticed in the sera of the diabetic group as compared to the normal group." (PMID 38234664, 2024).